FBXO38 (F-box protein 38)
Description:
Substrate recognition component of a SCF (SKP1-CUL1-F-box protein) E3 ubiquitin-protein ligase complex which mediates the ubiquitination and subsequent proteasomal degradation of PDCD1/PD-1, thereby regulating T-cells-mediated immunity. Required for anti-tumor activity of T-cells by promoting the degradation of PDCD1/PD-1; the PDCD1-mediated inhibitory pathway being exploited by tumors to attenuate anti-tumor immunity and facilitate tumor survival. May indirectly stimulate the activity of transcription factor KLF7, a regulator of neuronal differentiation, without promoting KLF7 ubiquitination (By similarity).
Synonyms: SP329; MOKA; FLJ13962; Fbx38; HMN2D; HMND6
Tractability: Antibody: the Human Protein Atlas places it where antibodies can reach. PROTAC: ubiquitination databases record sites on it; its protein half-life has been measured.
Gene: Protein-coding gene on chromosome 5 (148,383,826 to 148,442,850, forward strand). Ensembl gene ENSG00000145868.
Subcellular location: Cytoplasm, cytosol; Nucleus
Subcellular location (Human Protein Atlas): Nucleoplasm; Plasma membrane; Basal body; Primary cilium
Gene Ontology:
Molecular function: protein binding; ubiquitin-like ligase-substrate adaptor activity
Biological process: positive regulation of neuron projection development; positive regulation of T cell activation; positive regulation of T cell mediated immune response to tumor cell; protein K48-linked ubiquitination; SCF-dependent proteasomal ubiquitin-dependent protein catabolic process; protein ubiquitination
Cellular component: cytoplasm; nucleus; SCF ubiquitin ligase complex; cytosol
Genetic constraint (gnomAD): Loss-of-function variants: 47 observed, 111.16 expected, observed/expected ratio (o/e) 0.42, 90% interval 0.33 to 0.54. The upper end of that interval is the gene's LOEUF score, 0.54, which puts it in group 2 of 6, group 1 being the genes least tolerant of losing a copy. Missense variants: 976 observed, 1,364.7 expected, observed/expected ratio (o/e) 0.72, 90% interval 0.68 to 0.75. Synonymous variants: 412 observed, 477.26 expected, observed/expected ratio (o/e) 0.86, 90% interval 0.8 to 0.94.
Gene-disease validity (ClinGen):
ClinGen rates the evidence that FBXO38 causes each of these diseases.
distal hereditary motor neuropathy (autosomal dominant): Moderate.
Homologues: Orthologues: chimpanzee FBXO38 (99% identical), macaque FBXO38 (99% identical), rabbit FBXO38 (98% identical), dog FBXO38 (98% identical), guinea pig FBXO38 (96% identical), rat Fbxo38 (95% identical), mouse Fbxo38 (94% identical), pig FBXO38 (92% identical), tropical clawed frog fbxo38 (73% identical), zebrafish fbxo38 (68% identical).
Diseases named in the same sentence as FBXO38 in open-access papers:
FBXO38 is named in the same sentence as 18 diseases in open-access papers, as found by Europe PMC text mining. Sharing a sentence is not in itself a finding about the gene and the disease. The quoted sentences say what the papers report.
asthma (1 paper, 2025). "For asthma and COPD, one SNP rs11168048 located at 5q32 (harboring HTR4, FBXO38, and SPINK7) and two SNPs rs2122190 located at 5q23.1 (harboring PRR16) and rs6860087 located at 5q32 (harboring HTR4) were identified." (PMID 41295252, 2025).
chronic periodontitis (1 paper, 2015). A chronic inflammatory process that affects the tissues that surround and support the teeth. "Our findings provide direct evidence for the association of FBXO38 and AP3B2 with severe chronic periodontitis in the Han Chinese population." (PMID 26643602, 2015). "In this study, we conducted a two-stage comprehensive evaluation of the genetic susceptibility of FBXO38, AP3B2 and WHAMM with the diagnosis of severe chronic periodontitis." (PMID 26643602, 2015).
coronary artery disease (1 paper, 2025). "Explore FBXO38 in other vascular diseases: Investigate whether FBXO38's protective mechanisms extend to conditions such as coronary artery disease, peripheral artery disease, or stroke." (PMID 40313652, 2025).
distal hereditary motor neuropathy type 2 (1 paper, 2024). "Distal Hereditary Motor Neuropathy type 2 can be caused by any of four genes: HSPB8, HSPB1, HSPB3, or FBXO38 and affects fewer than one in a million people." (PMID 39480826, 2024).
distal muscular dystrophy (1 paper, 2022). "Another hint for the physiological role of FBXO38 comes from discoveries that several mutations in the FBXO38 gene drive early-onset distal muscular dystrophy." (PMID 35813202, 2022).
gallbladder cancer (1 paper, 2024). "We also confirmed that FBXO38 regulates PD‐1 ubiquitination to modulate its protein expression in gallbladder cancer cells." (PMID 39116343, 2024). "Further, we found that PTBP3 promoted immune escape in gallbladder cancer via ΔIL‐18, which decreased FBXO38 transcription levels in CD8+T cells to reduce FBXO38‐mediated degradation of PD‐1." (PMID 39116343, 2024).
lysosomal storage disorder (1 paper, 2024). "FBXO38 is associated with the group of neurological disorders, with its Online Mendelian Inheritance in Man (OMIM) phenotype characterized as Neuronopathy, distal hereditary motor, a type of lysosomal storage disorder." (PMID 39469623, 2024).
muscular atrophy (1 paper, 2022). The loss of muscle tissue due to inactivity or disease. "Mutants of FBXO38 found in patients with muscular atrophy interacted with ZXDA/B more strongly, especially after MLN4924 treatment." (PMID 35813202, 2022).
spinal muscular atrophy (1 paper, 2019). A motor neuron disease that affect the muscles, and characterized by muscle weakness and atrophy resulting from progressive degeneration and irreversible loss of the anterior horn cells in the spinal cord (i.e., lower motor neurons) and the brain stem nuclei. "Furthermore, a dominant mutation in FBXO38 that renders it unable to bind KLF7 causes spinal muscular atrophy (SMA), an inherited disorder characterized by progressive muscle weakness." (PMID 30804394, 2019).
tumor (17 papers, 2020 to 2025). "In the tumor microenvironment, FBXO38 deficiency led to elevated PD-1 levels and impaired T-cell functions, resulting in accelerated tumor progression in melanoma and colorectal cancer models." (PMID 39294504, 2024). "Melanoma and colorectal cancer mice models deficient in FBXO38 have higher tumor burden which related with higher PD-1 expression in their tumor-infiltrating T cells; PD-1 blockade rescued anti-tumor activities." (PMID 34639141, 2021). "Loss of FBXO38 significantly increases FGL1 abundance, which suppresses CD8+ T cell infiltration, enhances tumor growth, and promotes immune escape." (PMID 40534867, 2025). "Conversely, FBXO38 restoration enhances tumor sensitivity to anti-FGL1 therapy and amplifies the inflammatory response." (PMID 40534867, 2025). "In contrast, FBXO38 and CD8+ T cell infiltration are negatively correlated with TNM stage, highlighting FBXO38’s role in modulating tumor progression and immune responses." (PMID 40534867, 2025). "In FBXO38 conditional knockout mice, PD-1 levels were elevated in tumor-infiltrating T cells, which resulted in more rapid tumor development in the mice." (PMID 39759114, 2025). "Eliminating Fbxo38 in T cells accelerated tumor growth in mice due to increased PD-1 levels in the tumor-infiltrating T cells." (PMID 38638430, 2024). "In both human tumor samples and a mouse cancer model, the expression levels of FBXO38 and Fbxo38 were reduced in tumor-infiltrating T cells." (PMID 38638430, 2024). "T cells with conditional knockout of FBXO38 promoted mouse tumor progression due to upregulation of PD-1 in tumor infiltrating T cells." (PMID 36733484, 2023). "The transcriptional levels of FBXO38 were decreased in tumor infiltrating T cells in mice and human cancer tissues." (PMID 36733484, 2023). "Deletion of FBXO38 leads to faster tumor progression with increased PD-1 expression in tumor-infiltrating T cells." (PMID 35154081, 2021). "Mice bearing conditional knockout of Fbxo38 in their T cells had faster tumor progression due to high levels of PD-1 expression in tumor-infiltrating T cells." (PMID 35822050, 2021). "Our experimental systems included biochemical assays in both Jurkat T cells and HEK293 cells, a genetic model of conditional Fbxo38 knockout specifically in T cells, and multiple tumor models in which FBXO38’s role was assessed in T-cell exhaustion and immunotherapy." (PMID 39294504, 2024). "IL-2 restores Fbxo38 transcription and promotes PD-l degradation in tumor infiltrating T cells." (PMID 36733484, 2023). "Finally, an analysis of The Cancer Genome Atlas (TCGA) revealed that ZXDA/B are significantly mutated in several tumor types and that a large portion of these ZXDA/B cancer-associated mutations is located in the vicinity of the FBXO38-dependent degron." (PMID 35813202, 2022). "An increasing number of E3 ligases are being identified as the crucial regulators of tumor immune responses, including the membrane-associated RING-CH (MARCH) family of E3 ligases and F-box only protein 38 (FBXO38), which mediate the proteasomal degradation of programmed cell death protein 1 (PD-1)." (PMID 34943817, 2021). "Likewise, the E3 ligase FBXO38 controls T-cell anti-tumor responses by mediating PD-1 degradation." (PMID 34639141, 2021). "FBXO38 also modulates CD8+ T cell infiltration in vivo through the interferon-α response pathway, further underscoring its importance in anti-tumor immunity." (PMID 40534867, 2025). "FBXO38 ubiquitinates fibrinogen-like protein 1 (FGL1), negatively regulating its stability and thereby inhibiting tumor immune evasion." (PMID 40534867, 2025). "GSE62452 demonstrated that the higher expression levels of FBXO1, FBXO20, FBXO32, and FBXO45 were correlated with poorer tumor differentiation (N = 68), apart from FBXO22 and FBXO38." (PMID 35046938, 2021).
tumor (continued). "The ubiquitin ligase FBXO38 does not regulate the levels of the PD-1 receptor in T cells, indicating that factors other than PD-1 regulate the anti-tumor responses downstream of FBXO38." (PMID 39266770, 2024). "F-box only protein 38 (FBXO38) mediates PD-1 ubiquitination of T cells, and knockout of FBXO38 in such cells induces tumor progression in a mouse model due to increased PD-1 expression by tumor-infiltrating T cells." (PMID 32403421, 2020).
cancer (5 papers, 2015 to 2024). A tumor composed of atypical neoplastic, often pleomorphic cells that invade other tissues. "Given that such misexpression of centromeric chromatin may lead to chromosomal aberrations and possibly cancer-related malformations, there is a possibility that FBXO38 may provide a fine-tuning mechanism to avoid these anomalies." (PMID 35813202, 2022). "Our findings suggest that USP7 and FBXO38 may both be useful targets for inhibiting the growth of cancer cells with KIF20B overexpression." (PMID 30804394, 2019). "Via detailed analysis of ACA staining, we showed that the absence of FBXO38 leads to the stabilization of centromeric chromatin proteins, similar to the extent observed in human cancer cell lines." (PMID 35769260, 2022). "In support of this hypothesis, it has been shown that FBXO38 prevents cytokinesis and mitotic defects and that cancer cells lacking FBXO38 exhibited an increased frequency of multinucleated cells." (PMID 35813202, 2022).
neurogenetic diseases (1 paper, 2024). "FBXO38 was also discovered in rare neurogenetic diseases and neuromuscular diseases." (PMID 39469623, 2024).
FBXO38 also shares sentences with these, for which no sentence is quoted: breast carcinoma (1 paper); congenital myasthenic syndrome (1); neurological disorders (1); neuromuscular disease (1); peripheral artery disease (1); Stroke (1).